RO60 (Ro60, Y RNA binding protein)
Diseases named in the same sentence as RO60 in open-access papers (continued):
Sharing a sentence is not in itself a finding about the gene and the disease.
xerophthalmia (4 papers, 2013 to 2024). "Photosensitivity and xerophthalmia/xerostomia were the only features found to be positively associated with both anti-SSA/Ro60 and anti-Ro52/TRIM21." (PMID 24294139, 2013). "The frequency of dry eye/dry mouth, interstitial pneumonia, and pulmonary events over time differed between patients with various combinations of anti-Ro52 and anti-Ro60 antibodies." (PMID 38895121, 2024). "Compared with patients with isolated anti-Ro52 or anti-Ro60 antibodies, the patients with combined anti-Ro52 and anti-Ro60 antibodies were more likely to suffer from xerophthalmia and xerostomia." (PMID 36741231, 2023). "Consistently, in the present study, patients with both anti-Ro52 and anti-Ro60 reactivity were more likely to experience xerophthalmia and xerostomia and also had a significantly higher anti-La positivity compared with the patients with isolated anti-Ro60 or anti-Ro52 positivity." (PMID 36741231, 2023). "In contrast, photosensitivity and xerophthalmia/xerostomia showed a not statistically significant positive association with both anti-SSA/Ro60 and anti-Ro52/TRIM21." (PMID 24294139, 2013).
xerostomia (4 papers, 2011 to 2025). Dryness of the mouth resulting from reduced salivary secretion. "As shown for Balb/c mice, increased IFN-γ positive cells in the SG associated LNs of SJL/J following Ro60 peptide immunization also suggests the underlying mechanism of xerostomia is related to IFN-γ production." (PMID 21464925, 2011). "In particular, SSc patients who had antibodies to SS-A/Ro60 and SS-A/Ro52 demonstrated Sjögren’s syndrome (sialoadenitis, xerostomia)." (PMID 41283471, 2025). "Ro60-specific cells in the spleen of the abdominal area immunized Balb/c mice that developed xerostomia, produced consistently higher levels of IFN-γ and IL-12, compared with PBS or tailbase immunized mice." (PMID 21464925, 2011).
COVID-19 (3 papers, 2022 to 2025). A disease caused by infection with severe acute respiratory syndrome coronavirus 2. "None of the recovered COVID-19 children, and only one child at two different time points with COVID-19 had all three autoantibodies against Ro52, Ro60, La, and gastric ATPase autoantibodies." (PMID 35360001, 2022). "We found that some adults with COVID-19 had elevated antibodies to Sm-D3 as to well as Ro52, Ro60, and La." (PMID 35360001, 2022). "One child with acute COVID-19 that was seropositive for Ro52, Ro60, and La autoantibodies had a complex of neurological findings not fitting a clear diagnosis and received IVIG for autoimmune thrombocytopenia six days before the serum sample was collected." (PMID 35360001, 2022). "A small number of COVID-19 patients had antibodies against Ro52, Ro60, and La comprising the SSA and SSB rheumatological autoantigens." (PMID 35360001, 2022). "Several other autoantigens, including Ro52, Ro60, La, and GAD65 were detected less frequently (< 8%) in the adults with COVID-19." (PMID 35360001, 2022). "Approximately 50% of MIS-C children had Ro52, Ro60, and/or La autoantibodies, which were nearly absent in children with COVID-19 (1/59) and in children (0/8) who had recovered from COVID-19." (PMID 35360001, 2022). "Only one child with acute febrile illness not related to COVID-19, who was later diagnosed with SLE, showed Ro52, Ro60, and La autoantibodies, but not gastric ATPase autoantibodies." (PMID 35360001, 2022).
interstitial lung disease (3 papers, 2012 to 2025). A diverse group of lung diseases that affect the lung parenchyma. "In addition, the association between anti-Ro60 antibody and interstitial lung disease was increased almost threefold (OR, 2.86; 95% CI, 1.62 to 5.04; P = 0.0002; data not shown)." (PMID 22394602, 2012). "Patients with dual-positive anti-Ro52/Ro60 antibodies showed a markedly higher risk of several systemic complications, particularly sicca symptoms, interstitial lung disease (ILD), and hematologic involvement, compared to the double-negative group." (PMID 40901469, 2025). "The patients with anti-Ro60 (P = 0.044), anti-P (P = 0.012) and anti-dsDNA (P = 0.013) antibodies were less likely to develop Interstitial lung disease." (PMID 37344560, 2023).
nephritis (2 papers, 2013 to 2019). Inflammation of renal tissue. "Patients with active SLEDAI, nephritis, anti-dsDNA and anti-Ro60 positivity showed higher levels of sMER compared to controls." (PMID 24325951, 2013).
Oral ulcer (2 papers, 2024). Erosion of the mucous mebrane of the mouth with local excavation of the surface, resulting from the sloughing of inflammatory necrotic tissue. "Specific manifestations (oral ulcers) or autoantibodies profile (less frequent anti-Ro60+ antibodies), could indicate a different clinical phenotype in SLE patients with less inflammation and thus, with lower AGEs levels." (PMID 38474267, 2024).
overlap syndromes (2 papers, 2015 to 2024). "Other autoantibodies, including anti-U1-RNP, anti-PM-Scl, anti-Ku, anti-Ro60/SS-A, anti-Ro52/TRIM21, and anti-NOR 90 tend to be found in SSc-overlap syndromes as well as in other ARD, and are considered less specific for SSc." (PMID 25926833, 2015).
primary biliary cirrhosis (2 papers, 2022 to 2024). "The proportion of CD161+CD56+ NK cells in pSS patients with decayed tooth, fatigue, arthralgia, skin involvement, primary biliary cirrhosis, interstitial lung disease, anti‐SSA/Ro60 positive, anti‐SSB positive and high IgG was lower than that in negative patients." (PMID 38577997, 2024).
sarcoidosis (2 papers, 2024). Sarcoidosis is a multisystemic disorder of unknown cause characterized by the formation of immune granulomas in involved organs. "Similarly, autoimmune features have been reported in sarcoidosis, including the presence of autoantibodies directed against Ro52, Ro60, SSB, Rib-P, CCP, and β2-glycoprotein." (PMID 39309852, 2024).
TAFRO syndrome (2 papers, 2024). "Additionally, a recent report from Japan suggested that anti-SS-A/Ro60 antibodies may be involved in the disease characteristics of TAFRO syndrome, which may contribute to understanding the disease and selecting treatment methods in the future." (PMID 39451548, 2024).
atherosclerosis (1 paper, 2017). A disease characterized by the build-up of fatty material and calcium deposition in the arterial wall resulting in partial or complete occlusion of the arterial lumen. "As, in atherosclerosis, Ro60-associated s-RNYs generated by apoptotic macrophages are released in the blood of patients, we have investigated the extracellular function of the s-RNY/Ro60 complex." (PMID 28055017, 2017).
autoimmune hepatitis (1 paper, 2021). Hepatitis caused by autoantibodies. "In the scenario of autoimmune hepatitis, it is likely that these samples indeed did not contain anti-Ro60 antibodies or other autoantibodies to HEp-2 antigens." (PMID 34675922, 2021).
carotid atherosclerosis (1 paper, 2024). A thickening and loss of elasticity of the walls of carotid arteries that occur with formation of atherosclerotic plaques. "High levels of sCLP were associated with positive anti-SSA e anti-Ro60 with higher incidence of carotid atherosclerosis." (PMID 37603715, 2024).
chronic obstructive pulmonary disease (1 paper, 2019). A chronic and progressive lung disorder characterized by the loss of elasticity of the bronchial tree and the air sacs, destruction of the air sacs wall, thickening of the bronchial wall, and mucous accumulation in the bronchial tree. "Finally, in the Ro52+Ro60- group, AID was also the most represented group of disease, even if patients displayed a greater variety of pathologies such as infectious, neoplastic, pulmonary (chronic obstructive pulmonary diseases...) or cardiovascular diseases (myocardial infarction, strokes...)." (PMID 30915082, 2019).
Hypertension (1 paper, 2023). The presence of chronic increased pressure in the systemic arterial system. "A series of variables was associated, including hypertension, sex, anti‐SSA/Ro60 positivity, IgG levels, ALP, γ‐GT, and total cholesterol (p < 0.05)." (PMID 37904694, 2023). "In this study, it was observed that several risk factors were associated with the H. pylori infection, including age, gender, hypertension, ALP, γ‐GT, total cholesterol, LDL, anti‐SSA/Ro60 positive, hypergammaglobulinemia, and CRP levels." (PMID 37904694, 2023).
lymphoma (1 paper, 2024). A malignant (clonal) proliferation of B- lymphocytes or T- lymphocytes which involves the lymph nodes, bone marrow and/or extranodal sites. "In a cohort of 508 patients, individuals with combined reactivity for anti-Ro52/anti-Ro60 and anti-La antibodies had an increased risk of lymphomas, while anti-Ro52 single-positive test results were associated with inflammatory myositis, RA, and SjD." (PMID 39062948, 2024). "In SjD, the combined reactivity of anti-Ro52, anti-Ro60, and anti-La is associated with increased lymphoma risk." (PMID 39062948, 2024).
lymphopenia (1 paper, 2013). Reduction in the number of lymphocytes. "Anti-SSA/Ro60 was found to be positively associated with hypocomplementemia but negatively with antiphospholipid antibodies, whereas anti-Ro52/TRIM21 showed a positive association with lymphopenia and Raynaud's phenomenon and a negative relationship with anti-dsDNA antibodies." (PMID 24294139, 2013).
marginal zone lymphoma (1 paper, 2022). A usually indolent mature B-cell lymphoma, arising from the marginal zone of lymphoid tissues. "Peptide sequencing of anti-Ro60, anti-Ro52, anti-La and RF was combined with B cell repertoire analysis at the DNA, RNA and single cell level in blood B cell subsets, affected salivary gland and extranodal marginal zone lymphomas of mucosa-associated lymphoid tissue (MALT) of patients with SjS." (PMID 35144926, 2022).
melanoma (1 paper, 2020). A malignant, usually aggressive tumor composed of atypical, neoplastic melanocytes. "It has been repeatedly shown that patients affected by autoimmune RO60-dependent conditions have a higher frequency of malignancies, including melanoma, T-cell lymphoma, non-Hodgkin lymphoma, and breast carcinoma." (PMID 32423154, 2020).
otitis (1 paper, 2022). "In addition, the homology between Ro60 peptide TYYIKEQKL of HLA-DRB4*01:01 and Fusobacterium necrophorum, a rare causative agent of otitis and sinusitis, indicates the linkage of an oral biology homologue." (PMID 35330015, 2022).
parotitis (1 paper, 2022). Inflammation of the parotid glands. "We observed that a higher FS of LSG biopsy, ANA titer ≥ 1:320, positive RF, anti-SSA/Ro60, and anti-SSB values were more likely to occur in patients with parotitis, and that positive RF and anti-SSB were independent risk factors for parotitis in pSS." (PMID 36683822, 2022).
scleroderma (1 paper, 2024). Scleroderma is a rare autoimmune connective tissue disorder characterized by abnormal hardening of the skin and, sometimes, other organs. "While anti-CENP-A autoantibody (associated with scleroderma), and anti-Ro-60 (associated with SjD) were not informative in the IIM cohort, anti-Ro-52 autoantibody was present in 52% (n=11) of IIM-ILD patients." (PMID 39524452, 2024).
thrombosis (1 paper, 2025). "In the absence of clinical symptoms of Sjögren’s syndrome or thrombosis, we suppose that the positive anti-SS-A/Ro52, anti-SS-A/Ro60, and anti-β2 glycoprotein I IgG are considered concomitant serologic findings of SLE." (PMID 41425549, 2025).
infection (6 papers, 2010 to 2023). The state of being infected such as from the introduction of a foreign agent such as serum, vaccine, antigenic substance or organism. "The distribution of neither nELAVL nor RO60 was affected upon infection." (PMID 26894958, 2016). "Contrarily, the incidence rates of anti‐SSA/Ro60‐positive and hypergammaglobulinemia were much higher, while CRP was slightly higher in H. pylori‐positive infection compared to H. pylori‐negative pSS patients." (PMID 37904694, 2023).
cancer (5 papers, 2018 to 2023). A tumor composed of atypical neoplastic, often pleomorphic cells that invade other tissues. "Notably, Ro60 and Ro60-dependent autoimmune conditions are also implicated in cancer progression, yet more work is needed to better understand the contributions and potential interplay of Y RNA and Ro60 in tumorigenesis." (PMID 36754845, 2023). "RO60 is the best-known partner of Y RNAs involved in protein assembly, which is related to the cellular response to environmental stress and is considered a potential prognostic biomarker of immunity and cancer." (PMID 36110890, 2022). "Our current study evaluated the significance of disparities in the levels of ANA, anti-dsDNA, anti-Sm, anti-RO52, anti-RO60, anti-SSB, anti-Nuc, anti-His, anti-Rib, and anti-nRNP antibodies between the cancer group and the cancer-free control group at the time of cancer diagnosis." (PMID 32586407, 2020). "As the persistence of pre-existing transcripts blocks reprogramming via the RO60/ DDX6 axis, the molecular components in the axis could be a target for modulating cancer metastasis." (PMID 30273347, 2018). "Human Y RNAs interact with the autoimmune proteins SSB and RO60 that together form a ribonucleoprotein (RNP) complex termed RoRNP and Y RNAs also perform regulatory roles in DNA and RNA replication and stability, which has major implications for diseases including cancer." (PMID 35354369, 2022).
connective tissue diseases (5 papers, 2015 to 2024). "We agree with their ideas on the usefulness of recognizing specific AC-4 subpatterns with a focus on antibodies against SS-A/Ro60 and their association with connective tissue diseases." (PMID 35371074, 2022). "Anti-Ro60 and anti-Ro52 antibodies are associated with different connective tissue diseases (CTDs)." (PMID 36741231, 2023). "Indeed, epitope mapping of sera from SSA/Ro60-positive patients with connective tissue disease on the 3D structure of SSA/Ro60 did not reveal a single, convincing immunodominant B-cell epitope, and diagnostic value for any single SSA/Ro60 B-cell epitope (auto-epitope) has not been established." (PMID 35154130, 2022).
RO60 also shares sentences with these, for which no sentence is quoted: systemic sclerosis (5 papers); pulmonary fibrosis (3); Thrombocytopenia (3); Alzheimer disease (2); mixed connective tissue disease (2); AIDS (1); anemia (1); antiphospholipid syndrome (1); autoimmune gastritis (1); autoimmune thrombocytopenia (1); cardiovascular diseases (1); Castleman disease (1); congenital heart block (1); cutaneous lupus erythematosus (1); disseminated candidiasis (1); dry eye (1); encephalitis (1); glomerulonephritis (1); immune dysfunction (1); inflammatory myopathies (1); Kawasaki disease (1); long QT syndrome (1); membranoproliferative glomerulonephritis (1); mouth (1); multiple sclerosis (1); myocardial infarction (1); neurologic disease (1); Renal insufficiency (1); sialoadenitis (1); sinusitis (1).
A further 1 disease shares a sentence with RO60 in 1 paper.